CXCL8 (C-X-C motif chemokine ligand 8)
Diseases named in the same sentence as CXCL8 in open-access papers (continued):
Sharing a sentence is not in itself a finding about the gene and the disease.
tumor (continued). "Chemokine levels were not related to histological tumor classification, but tumors with no expression of EGFR and p21 had significantly increased levels of CXCL8 and CXCL6, respectively." (PMID 29850390, 2018). "For all assessed RCC tumor supernatants, the CXCL1 but not CXCL8 concentration correlated significantly (p = 0.014) with the migration of CXCR2-transduced NK cells relative to NGFR-transduced NK cells." (PMID 28923105, 2017). "Among genes differentially expressed between tumor samples with and without necrosis, a substantial number of hypoxia-related genes were found to be up-regulated, such as IL6, CXCL8 (IL8), SERPINE1 as well as genes involved in glycolysis (SLC2A3, LDHA)." (PMID 26485755, 2015). "Several angiogenesis-related genes like MMP1, MMP3, SFRP2, CXCL8, SERPINE1 and TNFAIP6 were up-regulated in tumors with necrosis, as identified among genes differentially expressed between tumor samples with and without necrosis." (PMID 26485755, 2015). "In renal cell cancer the levels of CXCL1, CXCL3 and CXCL8 were elevated compared to controls and in receptor negative (CXCR2−/−) mice there was a corresponding reduction in tumour growth." (PMID 21298036, 2011). "We have previously assessed the inflammatory profile for PDAC patients and only CXCL8, and PGE2 were found to be significantly enhanced, both in plasma and in the tumor tissue (data not shown)." (PMID 20976171, 2010). "A wide range of diffusible mediators released from transformed or non-transformed cells in the tumor niche are known to induce EMT, including growth factors (EGF), cytokines (TGF-β, TNF-α), chemokines (CXCL8, CXCL6), and lipid mediators (leukotriene B4 (LTB4))." (PMID 34567000, 2021). "The results showed that the expression of SH2D2A and GATA2 were upregulated (P = .0067 and P = .6021, respectively), while CXCL8, LIF, and VASH2 were downregulated in IVL tumor samples compared to nontumor tissue (P = .9281, P = .5406 and P = .0625, respectively)." (PMID 32372565, 2020). "Since rodents lack the CXCL8 gene, the functions of CAF-derived chemokines could not be identical between xenograft tumours and clinical GC tissues." (PMID 31147602, 2019). "An unfortunate effect could then be that CXCL8 and CXCL10 display pro-tumor activity in the absence of tumor-inhibiting type I IFNs." (PMID 28717003, 2017). "This could explain the down-modulation of CXCR2 in the ligand-rich tumor microenvironment, a phenomenon we have observed by exposing CXCR2-positive NK cells to recombinant CXCL8 (data not shown)." (PMID 28923105, 2017). "Furthermore, IL‐17 A may induce chemokine‐induced angiogenesis (CXCL8/CXCR2 axis) and promote tumor progression independent of the VEGF pathway." (PMID 38515019, 2024). "Immunoassay for chemokines secreted by ACKR1+ tumor cells showed a decrease in CXCL5 and CXCL8, and chemokine detection suggested the chemokines were bound by ACKR1 and internalized or immobilized on the cell surface rather than removed from the tumor microenvironment." (PMID 37006247, 2023). "The phenomenon that PGE2 potentiates the production of CCL2 and simultaneously reduces CXCL8 production by GM-CSF/IL-6 M-MDSC, could explain the observation that M-MDSC accumulate preferentially in PGE2-rich tumor site, rather than PMN-MDSC, although this hypothesis needs to be tested independently." (PMID 30936876, 2019). "In accordance with MIF and CXCL8, the clinical significance of CCL4 was not consistent, even opposite, in different cancers, suggesting that the biological functions of these cytokines in tumorigenesis and therapy response are complicated and labile and may be tumor type-specific." (PMID 40092701, 2025).
infection (2,869 papers, 1993 to 2026). The state of being infected such as from the introduction of a foreign agent such as serum, vaccine, antigenic substance or organism. "IL1A is a member of the cytokine family, which acts as a mediator of the immune response, while CXCL8 encodes for a member of a chemokine family, acting as a chemotactic factor by guiding the neutrophils to the site of infection (data from NCBI)." (PMID 39858269, 2025). "Pre-incubation with either HCMV variant for 24 h or 72 h before infection with A. fumigatus significantly and time-dependently suppressed gene expression and secretion of key cytokines such as CXCL8, VEGFA, IL-1α, IL-1β, IFN-γ, and TNF-α." (PMID 40980889, 2025). "CXCL8 encodes interleukin-8, a chemokine that attracts neutrophils to sites of infection and plays a role in inflammation and immune defenses against viruses." (PMID 40927453, 2025). "Bacteria penetrating the epithelial barrier into the intestinal wall matrix cause the release of the chemokine CXCL-8, which has a chemotactic effect on neutrophils, causing them to migrate to the site of infection." (PMID 37895400, 2023). "CXCL8 expression was significantly decreased following infection, and the loss of EGR1 resulted in an increase in CXCL8 transcription." (PMID 35746681, 2022). "For example, CXCL8 released from hepatocytes and LSECs upon infection causes chemotaxis of neutrophils and monocytes, changes endothelial cell permeability via cytoskeletal reorganization." (PMID 36451225, 2022). "Treatment of uroepithelial cells with CD4-PP altered the expression of CXCL8, encoding for the pro-inflammatory neutrophil recruiter IL-8, during in vitro infection." (PMID 35821354, 2022). "Infection with either virus also resulted in an induction of the pro-inflammatory genes CXCL8 (encoding IL-8), IL6 and TNF, albeit to a lesser extent in SARS-CoV-2-infected cells." (PMID 35840680, 2022). "The hMPV-infection of epithelial cells from the lung causes the secretion of the chemokines IL-8 (CXCL8) and CCL5 (RANTES)." (PMID 32545470, 2020). "Stimulation with IL-1β or infection with RV16 caused modest increases in CXCL8, while the addition of IL-1β to RV16-infected cells significantly augmented CXCL8 release." (PMID 30333178, 2019). "The SDSE infection, in both infected skin tissue and patient biopsies, resulted in high levels of the inflammatory markers CXCL8 and HMGB1, the latter of which is also associated with necrosis." (PMID 26601609, 2015). "Knockdown of Atg7 was associated with moderate reductions in CXCL8 production induced by RV16 infection or poly(I:C)." (PMID 25541728, 2014). "Lipase deficient yeast induced significantly higher CXCL8 gene expression at both time points in iDCs (p < 0.05), whereas mDCs increased CXCL8 mRNA levels only at 24 h post-infection (p < 0.05)." (PMID 21619700, 2011). "Through the release of CXCL8, infected cells not only establish a microenvironment conducive to viral propagation but also may render nearby uninfected cells more susceptible to infection." (PMID 39962077, 2025). "CSF IL‐8/CXCL8 is primarily secreted by monocytes, macrophages, epithelial, and endothelial cells, playing a role in neutrophil chemotaxis underlying the response to infection and tissue injury." (PMID 40781580, 2025). "Interestingly, low expression of CXCL8, like infection with TV, has been associated with a favorable prognosis in cervical cancer." (PMID 36774364, 2023). "faecalis, we observed lower CXCL8 than during infections caused by K-12 and E. faecalis alone." (PMID 34361936, 2021). "Here the authors demonstrate that rapid immune development in preterm babies is modulated by perinatal inflammation more than gut microbiota, and that lower CXCL8-producing T cells may identify infants susceptible to infection." (PMID 32152273, 2020).
infection (continued). "On the other hand, it is well established that CXCL8 induces chemotaxis in target cells, primarily neutrophils but also other granulocytes, causing them to migrate toward the site of infection while CXCL3 and CXCL2 controls migration and adhesion of neutrophils and monocytes." (PMID 32182886, 2020). "Together with IL-6, CXCL8 stimulation has been shown to reduce the capacity of activated DCs to induce T cell proliferation, potentially contributing to enhanced susceptibility towards secondary infections." (PMID 33613280, 2020). "Infection of MDMs with PRRSV caused a 6—fold increase of CXCL-8 secretion after 24 hours." (PMID 31442273, 2019). "Moreover, concerning CXCL1 and CXCL8 mRNA expression, it is obvious that the SM-HPBCs are more susceptible to S. aureus than the OM-HPBCs in the acute model of infection." (PMID 27446812, 2016). "After in vitro infection with L. braziliensis, CL patient neutrophils produced more reactive oxygen species (ROS) and higher levels of CXCL8 and CXCL9, chemokines associated with recruitment of neutrophils and Th1-type cells, than neutrophils from control healthy subjects (HS)." (PMID 27167379, 2016). "Furthermore, this infection actively stimulates an innate immune response which results in increases in expression of CXCL8 and TNF-α that have been implicated in ovine abortion following C. abortus infection." (PMID 25010668, 2014). "Notably, protein levels for CCL4 and CXCL8 were >20-fold and >40-fold higher respectively in choriodecidua from women with infection-associated PTL than idiopathic PTL and both strongly correlated with neutrophil abundance." (PMID 23451115, 2013). "In the saline group, there was minimal DEG overlap between 3 and 7 DPI relative to the pre-infection time point, with only seven shared DEGs that enriched to leukocyte migration and response to interleukin-1 (CXCL8 and CCL20) gene ontology (GO) terms." (PMID 40576342, 2025). "Unlike other cytokines that play a role in antiviral signaling, CXCL8 facilitates EV-D68 infection, which supports the function of the viral 5’UTR by promoting the cytoplasmic accumulation of hnRNP-K and its binding to viral RNA (vRNA)." (PMID 39962077, 2025). "Th17 cells emit the cytokine IL-17, which prompts epithelial cells, endothelial cells, and fibroblasts to generate numerous chemokines, including CXCL8 (IL-8), thus enlisting neutrophils to the locus of infection to perform immunological phagocytic functions." (PMID 41346618, 2025). "infection alters the secretome of decidual stromal cells, leading to an overproduction of CXCL8 and CCL2, which in turn impairs trophoblast invasive capacity." (PMID 40943115, 2025). "The expression of IL-1β, IFN-α2, IFN-γ, TNF-α, MCP-1 (CCL2), IL-6, IL-8 (CXCL8), IL-10, IL-12p70, IL-17A, IL-18, IL-23, and IL-33 was assessed in apical washes at different time points after infection using a 13-plex immunoassay." (PMID 40143308, 2025). "Here the authors show in vitro that infection by the enterovirus, EV-D68, induces CXCL8/CXCR1/2 signaling and translocation of host factor, hnRNP-K, to the cytoplasm as a means to facilitate viral replication." (PMID 39962077, 2025). "We further confirmed the essential role of CXCL8 expression in EV-D68 infection in diverse immortalized cell lines, including A549, BEAS-2B, and CALU-3 respiratory cells and other EV-D68-permissive cell lines, namely, HEK293T cells and RD cells." (PMID 39962077, 2025). "In the transcriptomic analysis of rabbits at 6 dpi with MPXV, pathways related to pathogenic infection and inflammatory response were enriched, and inflammatory genes such as IL1A, IL1B, and CXCL8 were significantly upregulated." (PMID 41157589, 2025). "IL-8 (also called CXCL8) is the most potent chemokine recruiting neutrophils to the site of damage or infection, which is called chemotaxis." (PMID 41142152, 2025).
infection (continued). "CCL-3 and CXCL-8 are chemokines that attract macrophages and neutrophils, respectively, which can increase inflammation at the infection site to eliminate ETEC." (PMID 40619401, 2025). "In turn, IL-17A induces CXCL8 and other chemokines to recruit and activate neutrophils at sites of infection." (PMID 39966757, 2025). "The chemotaxis of neutrophils towards the infection site depends on the binding of CXCL-8 to the G protein-coupled cell surface receptors CXCR1 and CXCR2 expressed by infected epithelial cells." (PMID 40475997, 2025). "As one of the most potent chemokines, CXCL8 normally serves as a key factor in responding to infection." (PMID 39741182, 2025). "In vivo and in murine organoids, the bladder mounts a rapid pro-inflammatory response to infection, including production of IL1β, IL-6, IL-8 (CXCL8), and TNF104,105." (PMID 40766562, 2025). "Chemokines such as CXCL1, CXCL2, and CXCL8 (IL-8) are potent neutrophil chemoattractants and play a crucial role in recruiting neutrophils to sites of infection or inflammation." (PMID 41180630, 2025). "CXCL8, also known as IL-8, is a strong neutrophil chemoattractant, which triggers the recruitment of neutrophils and other granulocytes to the site of infection, promotes neutrophil degranulation and enhancements in their phagocytic functions." (PMID 40406273, 2025). "IL-8 (CXCL8), which is secreted primarily by epithelial cells in the lung, plays a key role in neutrophil recruitment and activation during infection." (PMID 40558960, 2025). "The activation of these receptors promotes the migration of immune cells to sites of infection or inflammation, making the CXCL8/CXCR1-2 axis crucial in the host response to infections." (PMID 39962077, 2025). "IL-8 (also known as CXCL8) is a pro-inflammatory chemokine produced by macrophages, endothelial cells, and epithelial cells in response to infection or injury, inducing granulocyte chemotaxis, phagocytosis, and oxidative burst." (PMID 40868199, 2025). "Of these, CCL20, CXCL10, CXCL1, CXCL8, and IL-18 showed higher levels compared to uninfected epithelium 24 h after infection." (PMID 40586572, 2025). "Despite the profound lack of interferon induction, Ebola significantly induced inflammatory cytokines, including IL6 and CXCL8/IL8, by 48 hours post-infection." (PMID 41279810, 2025). "Its downstream effects include upregulation of chemokines such as CXCL1 and CXCL8, which recruit neutrophils to sites of infection, and stimulation of epithelial cells to produce antimicrobial peptides." (PMID 40917923, 2025). "In this study, we revealed that a CXCL8 signaling axis in respiratory cells drives proviral effects during infection with human viruses, highlighting the potential of this axis as a universal target for drugs combating respiratory virus infections." (PMID 39962077, 2025). "IL-8, also called CXCL8, is a pro-inflammatory cytokine predominantly secreted by macrophages, which can also act as a chemokine in infection." (PMID 41369364, 2025). "The IL- 1β/IL- 1RA and CXCL8/CXCL10 ratios emerge as promising biomarkers to distinguish between infection and inflammation, with potential in targeted wound care." (PMID 40200385, 2025). "Among these, CXC‐chemokine ligand 8 (CXCL8, also known as IL‐8) stands out as a potent chemoattractant that recruits neutrophils to sites of infection." (PMID 41498036, 2025). "Interleukin-8 (IL-8), or CXCL8, is primarily responsible for the robust recruitment of neutrophils to sites of infection and inflammation in the lung." (PMID 41176818, 2025). "Chemokine CXCL8 (C-X-C motif chemokine ligand 8), also known as Interleukin-8 (IL-8), is a pro-inflammatory chemokine that facilitates the recruitment of neutrophils to areas of inflammation, infection, or injury." (PMID 40573881, 2025). "The chemokine CXCL8, also known as interleukin-8 (IL-8), is a pro-inflammatory chemokine that plays a crucial role in recruiting neutrophils to sites of inflammation, infection, or injury." (PMID 40006729, 2025).
infection (continued). "Beyond invasion, we also measured CXCL8 concentrations in the supernatant to assess the host response to infection with our BECC-modified Shigella, which showed the same pattern as invasion." (PMID 38946947, 2024). "The level of expression of IL8 (CXCL8) remained high in case of exposure to cytokines followed by infection, suggesting that the level of inflammation remains constant." (PMID 39244776, 2024). "In a similar vein, HuN4 infection led to a notable increase in the transcriptional levels of CXCL8, when contrasted with the control group or the HuN4-F112 vaccinated pigs." (PMID 38715098, 2024). "Gene expression for interleukin-8 (CXCL8), which is an important chemokine that activates and recruits neutrophils into the site of infection, depends on the elevation of cytosolic Ca2+ concentration." (PMID 38672379, 2024). "In the early stages of infection, IL-1β produced by macrophages binds IL-1R on airway epithelial cells and stimulates them to produce neutrophil-recruiting chemokines such as CXCL8, a cascade which can be amplified with chronic infection." (PMID 39015565, 2024). "CXCL8 is a chemokine that holds a critical role as a human neutrophil chemoattractant, especially during responses to infection and tissue damage." (PMID 38281996, 2024). "Our data add nuance to these reports by implicating H. pylori LPS with CXCL-8 upregulation, suggesting possible roles for glycan structures in pathogenesis, chronic infection, and cancer development upon infection." (PMID 38572314, 2024). "Adding 25–100 μL (0.5–2 MOI) RV16 significantly induced CXCL8 protein production in both the virus dose- and infection time-dependent manner (p < 0.001)." (PMID 39598462, 2024). "Our data show that JCPyV-infected choroid plexus epithelial cells at 7 days post-infection, which represents two full viral life cycles, secrete a signature of proinflammatory chemokines, including CXCL8, CXCL5, CXCL6, and CCL2." (PMID 38874395, 2024). "Subsequently, we analyzed CXCL8 expression in the epithelial compartment of the mucosoid/DC co-cultures upon infection with H. pylori wt or the ΔrfaE mutant as well as the T cell phenotype." (PMID 39288239, 2024). "CXCL-8 is a pro-inflammatory cytokine that is upregulated to promote an inflammatory response and recruit neutrophils to the site of infection." (PMID 38572314, 2024). "We chose 4 of these LW6-sensitive genes (LIF, EDN1, IL36G and CXCL8) for validation by quantitative RT-PCR on an independent group of infections." (PMID 38902255, 2024). "CXCL8 is widely regarded as a potent neutrophil chemotactic agent that promotes the aggregation of neutrophils and other granulocytes to the site of infection." (PMID 38698849, 2024). "CXCL8, also known as interleukin-8 (IL-8), represents a pivotal molecule that triggers and activates neutrophils in response to tissue damage or infection." (PMID 39840040, 2024). "The inhibitory effects of cilomilast on 100 μL (2 MOI) RV16-mediated CXCL8 production were overcome by a relatively high dose RV16 infection." (PMID 39598462, 2024). "This recruitment is driven by ELR+ chemokines such as CXCL1, CXCL5, and CXCL8, which are elevated in response to these infections." (PMID 39286256, 2024). "In contrast, in AA-supplemented cultures from severe asthmatic donors, viral replication was enhanced whereas PTGS2 expression and PGE2 release were unchanged and CXCL8/IL-8 was significantly reduced in response to RV16 infection." (PMID 38179897, 2024). "As the primary cells to recognize antigens, macrophages are likely the first to release CXCL8 at sites of infection or injury." (PMID 38715098, 2024). "CXCL8 plays a crucial role in the immune response by attracting and activating neutrophils at the infection site." (PMID 39403383, 2024). "In fish as in mammals, the chemokine interleukin-8 (also known as CXCL8) is involved in recruiting neutrophils to the site of infection." (PMID 38193283, 2024).